CRP (C-reactive protein)
Diseases named in the same sentence as CRP in open-access papers (continued):
Sharing a sentence is not in itself a finding about the gene and the disease.
tumor (continued). "Campanacci stage, tumor maximum diameter, alkaline phosphatase, and C-reactive protein (CRP) were significantly associated with the high NLR and PLR." (PMID 30961549, 2019). "Those were serum albumin, fibrinogen, C-reactive protein (CRP), the number of white blood cells, neutrophils, lymphocytes, tumor size, and tumor mutational burden." (PMID 31683809, 2019). "As an acute-phase protein, CRP is the prevailing marker of inflammation, and various studies have reported that CRP is increased in patients with tumours and that it is associated with a poor prognosis." (PMID 30486825, 2018). "High sensitivity CRP (hsCRP), tumor CRP and CRP gene polymorphism should be evaluated for better insight into risk of recurrence, treatment response and toxicity." (PMID 30138391, 2018). "Second, a reverse causality model has been proposed wherein tumor growth and invasion induces tissue inflammation, leading to the increase in CRP levels." (PMID 29668751, 2018). "In the present study, CRP was strongly correlated to fibrinogen and both were strongly associated with decreased overall survival CRP remained significant after adjustment with AJCC tumor stage in a multivariable regression model." (PMID 29701260, 2018). "Univariate analyses displayed that the postoperative 5-year survival was associated with comorbidities, tumor size, operative time, intraoperative blood loss, postoperative serum CRP, TNM stage, adjuvant therapy, and postoperative complications." (PMID 28484712, 2017). "The elevated CRP/Alb was significantly associated with a more advanced tumor stage (p = 0.001), fewer patients with ideal cytoreductive surgery (p = 0.049), the presence of ascites (p = 0.009) and higher serum CA-125 level (p = 0.002)." (PMID 28431566, 2017). "We further analyzed the association between CRP and clinicopathologic factors in different tumor sites (buccal, tongue, and other locations)." (PMID 28209200, 2017). "High pretreatment CRP was associated with significantly worse FFR and CRP serum concentrations increased significantly in case of tumor recurrence." (PMID 28514756, 2017). "The correlation of C-reactive protein decrease with significantly improved OS underlines the close link between inflammation and tumor control." (PMID 29098441, 2017). "Elevated levels of CRP are significantly associated with poor survival in various tumor types, including EC." (PMID 28740506, 2017). "Regarding the tumor subsites, the elevation of CRP in buccal cancer had the most promising association with most clinicopathologic factors." (PMID 28209200, 2017). "Recent evidence has supported systemic tumor-associated inflammatory response markers, including C-reactive protein (CRP) and the Glasgow prognosis score (GPS) as able to predict the outcome in ESCC patients treated with surgery." (PMID 29152134, 2017). "In other tumor subsites, the CRP elevation (CRP ≥ 5.0 mg/L) was significantly associated with advanced pathological tumor status (p = 0.001), tumor stage (p = 0.009), and bone invasion (p < 0.001)." (PMID 28209200, 2017). "Increased CRP/Alb (≥0.68) was associated with advanced stage, residual tumor, ascites, elevated serum carbohydrate antigen(CA)-125 level, GPS, and mGPS (all p < 0.05)." (PMID 28431566, 2017). "Our study revealed that CRP/PNI ratio was associated with tumor length (P <0.001), TNM stage (P = 0.012), GPS (P <0.001), CRP (P <0.001), PNI (P <0.001), NLR (P <0.001) and PLR (P <0.001)." (PMID 27557504, 2016). "High levels of preoperative serum CRP were significantly associated with well-established clinicopathologic features, including gender, advanced tumor stage, and elevated carcinoembryonic antigen and carbohydrate antigen 19-9 levels (P < 0.05)." (PMID 27733196, 2016). "Several markers have been reported to reflect the association of inflammation and tumor, such as interferon-gamma/interleukin-4 ratio and inflammation-based prognostic score based on CRP and albumin levels." (PMID 27125872, 2016).
tumor (continued). "In univariable analysis CRP was significantly associated with the incidence of tumor recurrence (p < 0.0001) and remained significant regarding recurrence (p = 0.023; CI 95 % 1.0–2.3) in multivariable analysis." (PMID 27091202, 2016). "Advanced tumor stage was associated with a poorer histologic differentiation, higher CRP level, lower albumin level, and inferior progression‐free survival rate (PFSR)." (PMID 26799163, 2016). "In particular in a multivariate analysis, patients with a CRP > 8 mg/l were at significantly higher risk of tumor progression (HR 2.18; 95% CI 1.40–3.40; p = 0.001) and death (HR 2.0; 95% CI 1.28–3.12; p = 0.002) than patients with a CRP ≤ 8 mg/l." (PMID 27924136, 2016). "A validation of our finding with larger cohorts and integration of putative risk factor would further elucidate CRP a surrogate for tumor progression." (PMID 27091202, 2016). "From another point of view, the association between CRP and tumor characteristics in ER patients varied from that in LR patients reflected some diversities of these two types of HCC recurrence." (PMID 25602444, 2015). "In our meta-analysis, we evaluated the association between CRP and survival outcome of patients with different tumor stages or treated with different therapies." (PMID 26235332, 2015). "CRP and Alb are easily obtainable biomarkers associated with the lung parenchyma lesion, caused by the tumor presence." (PMID 26339617, 2015). "For HCC patients with elevated serum CRP, the risk of ER rise significantly when the maximal tumor dimension was more than 5cm." (PMID 25602444, 2015). "The measured serum tumor markers such as LD, TK, CRP, and B2m are associated with functional imaging markers, and LD, TK, and CRP are useful in differentiating DLBCL from FL." (PMID 24454777, 2014). "This view is supported by another study, describing the association between elevated CRP up to 31 months after tumor removal and shorter survival time." (PMID 25340395, 2014). "Among CRC cases, maximal tumor size was an independent determinant of serum NGAL (p = 0.028) but this association was reduced after adjustment for CRP (p = 0.11)." (PMID 25472811, 2014). "In our previous studies, we have clearly demonstrated that elevated serum CRP is associated with advanced tumor status, skin invasion, and bone invasion and have shown significant correlations between the CRP level, DFS, and OS." (PMID 25061977, 2014). "A close association was also observed between a high CRP level (CRP≥5.0 mg/L) and recurrent tumor status (P = 0.026), recurrent nodal metastasis (P = 0.014), distant metastasis (P<0.001), and recurrent tumor stage (P<0.001)." (PMID 25061977, 2014). "The patient subgroup with positive levels of both SCC-Ag and CRP demonstrated a profoundly significant association with clinical stage (P<0.001), clinical tumor status (P<0.001) and nodal status (P<0.001) compared to other patient groups." (PMID 23383155, 2013). "CRP levels are closely associated with the predisposing factor of tumor recurrence in HCC patients with malignant portal vein invasion after surgical resection, and lung metastasis is common." (PMID 23618082, 2013). "A close association was observed between a higher CRP level (CRP≥5.0 mg/L) and clinical stage (χ2 trend test: P = 0.005), clinical nodal status (χ2 trend test: P = 0.003), and tumor differentiation (χ2trend test: P = 0.014)." (PMID 23383155, 2013). "Based on the multivariate model, a risk score can be calculated using the formula: Risk Score = 0.545* (tumor number) + 0.331* (Choi response) + 0.093* (MELD score) + 0.44*ln (CRP)." (PMID 24367506, 2013).
tumor (continued). "A SCC-Ag level ≥2.0 ng/ml and a CRP level ≥5.0 mg/L were significantly associated with clinical stage (P<0.001), clinical tumor status (P<0.001), and clinical nodal status (P<0.001)." (PMID 23383155, 2013). "CRP level was closely associated with the predisposing factor of tumor recurrence in HCC patients with malignant portal vein invasion after a surgical resection, and lung metastasis was common." (PMID 23618082, 2013). "The CRP-level, stratified to three subgroups (CRP ≤ 4, 4–10, and >10 mg/l), correlated significantly with tumour stage (p < 0.001), the risk of presenting nodal disease (2.1, 3.1, and 16.4%) and distant metastasis (2.9, 8.6, and 30.0%; p < 0.001)." (PMID 22958305, 2012). "After a mean follow-up of more than 4 years, the tumour-associated death rates were 12.4, 24.8, and 50.7% in the CRP ≤4, 4–10, and >10 mg/l groups (p < 0.001, Chi2 test)." (PMID 22958305, 2012). "It has been confirmed that initial CRP values were directly associated with total mortality rate in neoplastic disease." (PMID 22574625, 2012). "Tumor growth can cause tissue inflammation around the tumor and hence increase plasma levels of CRP." (PMID 22912790, 2012). "On univariate overall survival analysis, performance status (P<0.05), T stage (P<0.001), tumour size (P<0.01), grade (P<0.001), necrosis (P<0.001), C-reactive protein (P<0.001) and mGPS (P<0.001) were significantly associated with overall survival." (PMID 22166802, 2012). "The extent of tumor progression in various mouse groups was highly reflected by CRP levels (thus implying a diagnostic/prognostic role for CRP)." (PMID 19341447, 2009). "We provided a novel, strong evidence that CRP serves as a sensitive diagnostic/prognostic marker both for tumor progression and responsiveness to chemotherapy in solid tumors." (PMID 19341447, 2009). "An elevated C-reactive protein was associated with greater tumour length (P<0.01), advanced TNM stage (P<0.01) and the operability of the tumour (P<0.001) and a poorer ECOG-ps (P<0.05)." (PMID 18268490, 2008). "A chronic inflammatory cellular infiltrate was noted in 40 (75%) tumour samples and was associated with elevated levels of serum CRP and sTNF-R." (PMID 17088911, 2006). "An elevated C-reactive protein was associated with a greater number of patients with advanced tumour stage (P<0.01), increased grade (P<0.05), poorer performance status (P<0.01) and consequently a high UISS (P<0.01)." (PMID 16523196, 2006). "In summary, an elevated preoperative C-reactive protein was associated with increased tumour stage, interleukin-6 and interleukin-10 concentrations." (PMID 17003778, 2006). "An elevated preoperative C-reactive protein was associated with increased tumour stage, interleukin-6 and interleukin-10 concentrations." (PMID 17003778, 2006). "On univariate analysis, sex (P<0.05), tumour size (P<0.05), vascular invasion (P<0.001), preoperative (P<0.001) and postoperative (P<0.001) C-reactive protein concentrations were significantly associated with survival." (PMID 15597096, 2005). "On multivariate analysis, age (P=0.012), tumour type (0.002), weight loss (P=0.056), C-reactive protein (P=0.047), Karnofsky performance status (P=0.002) and fatigue (P=0.046) were independent predictors of survival." (PMID 12177792, 2002). "Significant differences in baseline characteristics were observed across risk groups: low-risk patients exhibited higher Body Mass Index (BMI) and albumin levels, whereas high-risk patients had larger tumor sizes, elevated CRP, Lactate Dehydrogenase (LDH), NLR, and C-PLAN scores." (PMID 41875627, 2026). "Integration of CRP into multimodal preoperative assessment algorithms could improve surgical planning and reduce the risk of inadvertent tumour dissemination." (PMID 41976375, 2026). "CRP is not only a systemic inflammation marker but is also tightly linked to tumor immunity." (PMID 41055020, 2026).
tumor (continued). "Additionally, High levels of CRP and HSP90α were also associated with advanced tumor stage and higher Child-Pugh classification." (PMID 41458972, 2025). "The association of the ceramides and sphingomyelinswith tumour markers and CRP was investigated." (PMID 40821650, 2025). "Elevated CLR integrates two critical biological processes: C-reactive protein (CRP) elevation reflects IL-6-driven hepatic synthesis in response to tumor-associated inflammation, while lymphocytopenia indicates immunosuppression and reduced cytotoxic T-cell activity." (PMID 41451214, 2025). "CRP levels of >20 mg/L have a sensitivity of 75% and specificity of 96%, whereas fibrinogen levels of >600 mg/dl have a sensitivity of 67% and specificity of 91% for ischemic stroke associated with neoplasia." (PMID 40584524, 2025). "CRP has been linked to tumor malignancy and physical cachexia." (PMID 40786260, 2025). "Additionally, sICAM‐1 was negatively associated with tumor budding among female patients while CRP was positively associated with tumor budding among male patients." (PMID 40985344, 2025). "Moreover, the markedly elevated levels of CRP in individuals with GBM indicate the presence of systemic inflammation associated with the tumor." (PMID 38933650, 2024). "Tumor cells can cause inflammation and increase serum CRP levels." (PMID 39687883, 2024). "They mentioned that elevated serum CRP levels might be caused by tumor necrosis or local tissue damage and upregulated in response to elevated interleukin-6 levels, which promotes tumor growth by inducing multiple signaling pathways." (PMID 38791922, 2024). "It is hypothesized that the elevated inflammatory markers [such as C-reactive protein (CRP)] associated with AL stimulate tumour proliferation and neoangiogenesis which leads to higher recurrence rates and reduces the overall survival/disease-free survival." (PMID 38756356, 2024). "Despite these limitations, our findings suggest that a high C reactive protein-to-albumin ratio is associated with unfavorable clinicopathological tumor characteristics and that this ratio correlates with established scores, which have been previously assessed in the literature." (PMID 39064483, 2024). "In line with the high immunogenicity of MSI tumours, we also saw significant associations between high CRP levels and a high degree of tumour infiltration by macrophages in both the exploration and the validation cohort measured in two different ways, emphasizing the consistency of these findings." (PMID 39613865, 2024). "Finally, based on the independent risk factors (SII, PNI, tumor size, tumor necrosis, surgical mode, pathological type, CRP, AJCC stage and Fuhrman grade) affecting the prognosis of patients with RCC, a nomogram prediction model was constructed and verified." (PMID 39443568, 2024). "Elevated serum CRP has been reported to be associated with various unfavorable prognostic factors, such as a larger tumor size, aggressive histopathological type, and high serum levels of interleukin-6, which plays a crucial role in tumor growth and chemoresistance." (PMID 39043707, 2024). "In both cohorts, a high CRP level was significantly linked to tumours of the MSI subtype." (PMID 39613865, 2024). "Recent studies have reported hypersensitive C-reactive protein (hs-CRP) linked to clinicopathological characteristics and nutritional status of the tumor, but its clinical significance in GC remains unclear." (PMID 37293590, 2023). "Additionally, in a preliminary study, elevated CRP level was linked to tumor progression and poor survival in patients with ESCC." (PMID 38037003, 2023). "Contrary to our hypothesis, though, the addition of CRP to the experimental models associated with tumor regression and anti-metastatic effects." (PMID 37006231, 2023).
tumor (continued). "CRP—an acute phase reactant as well as a marker of chronic inflammation—has been found to be associated with a poorer prognosis in several studies of patients with solid tumours and is proposed to be an indicator of a high tumour load." (PMID 37084178, 2023). "Tumour growth can cause widespread tissue inflammation and therefore increase CRP levels." (PMID 37083267, 2023). "The underlying mechanisms were as follows: tumor antigens activate the immune response; tumor growth induces tissue inflammation; tumor cells secrete inflammatory cytokines that directly or indirectly increase the CRP level." (PMID 37015898, 2023). "In addition to CRP-related metrics, the presence of liver lesions and a higher tumor load were associated with shorter survival, i.e., worse prognosis." (PMID 38001689, 2023). "The C-reactive protein (CRP) is produced by hepatocytes as a systemic response to cytokine stimulation (particularly interleukin-6) from tumor microenvironment leukocytes, and has been associated with progressive disease and relatively poor survival in patients with different malignancies." (PMID 35562926, 2022). "The baseline determination of serum CRP seems to be useful to identify a subgroup of patients who might be predisposed to early tumor progression." (PMID 34882287, 2022). "Extensive tumor invasion and necrosis may also positively upregulate systemic inflammation, and the resultant elevated CRP level is linked to a poor OSCC prognosis." (PMID 35242712, 2022). "In the multivariate analysis, the following variables were confirmed to be independent risk factors for AL: Tumor location (p < 0.001), Age (p = 0.012), Sex (p = 0.041), Hemoglobin (p = 0.001), C-reactive protein (p = 0.040), LCR (p = 0.003) and NRS2002 (p = 0.006)." (PMID 35870933, 2022). "While the underlying mechanisms are not yet fully understood, studies suggest that high CRP is correlated with an immunosuppressive tumor microenvironment via the infiltration of immune suppressor cells (including regulatory T cells and tumor-associated microphages)." (PMID 35978814, 2022). "We hypothesize, that the proinflammatory immune response to the tumor causes a systemic inflammatory response that can be detected by measuring serum CRP." (PMID 35461024, 2022). "However, the reprogramming of lipid metabolism by tumour cells affects serum lipid levels in the body, which are inversely associated with C-reactive protein (CRP) levels in IBD." (PMID 35893893, 2022). "In our series, we therefore hypothesized that in a number of patients, high CRP levels were a consequence of tumour-associated inflammation, which at the same time, also affected bone health and BMD." (PMID 36143059, 2022). "Interestingly, the BR-B patients presented with significantly higher CRP levels, suggesting a stronger tumor-associated inflammation in the BR-B patients." (PMID 36094690, 2022). "Thus, it is consistent that tumour extent is associated with CRP levels as confirmed in the present study." (PMID 33740951, 2021). "When correlating the presence of neutrophils and macrophages with the patients’ outcomes, a higher density of CD66b(+) neutrophils, intratumoral as well as in the tumor stroma, was associated with elevated levels of C-reactive protein and a higher white blood cell count." (PMID 34885082, 2021). "Elevated CRP levels as part of tumour-associated inflammation is a well-known phenomenon." (PMID 34887479, 2021). "Patients with CRP ≥ 5 mg/L were found in all diagnostic groups except for neoplasms." (PMID 34830693, 2021). "We further aimed to examine whether differences in preoperative serum CRP levels may improve preoperative risk stratification in tumours with given grading." (PMID 34887479, 2021). "High CRP is also associated with numerous poor prognostic indicators including larger tumor size, higher grade and stage, lymphatic involvement, microvascular invasion, and aggressive histopathological findings such as spindle morphology and sarcomatoid morphology." (PMID 34512646, 2021).